NDUFS8 (NADH:ubiquinone oxidoreductase core subunit S8)
Diseases named in the same sentence as NDUFS8 in open-access papers (continued):
Sharing a sentence is not in itself a finding about the gene and the disease.
tumor (10 papers, 2014 to 2025). "Importantly, NDUFS8 has been reported to have an association with tumor relapse in patients with estrogen receptor α-positive breast cancer." (PMID 36557887, 2022). "Interestingly, NDUFS8 has been associated with tumor relapse in patients with estrogen receptor α-positive breast cancer." (PMID 25050621, 2014). "The TCGA-HCC dataset revealed that NDUFS8 transcript levels were significantly elevated in tumor tissues compared to normal liver tissues." (PMID 40914145, 2025). "The analysis focused on a comparative assessment of NDUFS8 expression in NSCLC tumor tissues (“T”) and adjacent normal lung epithelial tissues (“N”)." (PMID 40258810, 2025). "An extensive evaluation of NDUFS8 protein blotting data across all 15 tissue sets supported a significant upregulation in NDUFS8 protein within NSCLC tumor tissues." (PMID 40258810, 2025). "In conclusion, in vivo gene silencing of NDUFS8 via AAV delivery significantly inhibited xenograft tumor growth and induced apoptosis, supporting NDUFS8 as a critical promoter of HCC progression." (PMID 40914145, 2025). "A comprehensive evaluation across all ten patient samples confirmed the significant upregulation of NDUFS8 protein in HCC tumor tissues." (PMID 40914145, 2025). "Fresh tumor xenografts were processed, revealing a substantial reduction in NDUFS8 mRNA and protein expression in pNSCLC1 xenograft tissues treated with aav-shNDUFS8." (PMID 40258810, 2025). "Western blot analysis of tumor samples from six representative patients (designated T1 to T6) showed a marked increase in NDUFS8 protein levels." (PMID 40914145, 2025). "Furthermore, Western blotting analyses unveiled a notable increase in NDUFS8 protein levels within NSCLC tumor tissues from three representative patients, denoted as “T1” to “T3”." (PMID 40258810, 2025). "Single-cell RNA sequencing confirmed NDUFS8 upregulation in cancerous cells of NSCLC tumor." (PMID 40258810, 2025). "In addition, we found that many genes associated with ATP synthesis, such as ATP5F1D, ATP5ME, and ATP5MF, and genes associated with NADH oxidation, such as NDUFS8, NDUFB10, and NDUFC1, were overexpressed in LIHC and LUAD tumor tissues." (PMID 33262783, 2020). "The expression of ABHD10 and NDUFS8 decreased only after long-term tumor treatment with si-hVDAC1." (PMID 31661894, 2019). "To further investigate NDUFS8 expression in HCC, we analyzed tumor and adjacent normal liver tissues from 10 patients with primary HCC (n = 10)." (PMID 40914145, 2025). "When we performed a paired tissue analysis, the expression of NDUFS8 in LUADLUSC cancer tissues (“Tumor”) was notably higher than in the corresponding adjacent normal tissues (“Normal”)." (PMID 40258810, 2025). "Quantitative PCR analysis revealed that NDUFS8 mRNA levels were significantly upregulated in tumor tissues compared to matched non-tumorous liver tissues." (PMID 40914145, 2025). "Our examination of the TCGA LUADLUSC dataset (including both LUAD and LUSC) revealed that the quantity of NDUFS8 transcripts in cancerous tissues (“Tumor”) was significantly higher than in normal lung tissues (“Normal”)." (PMID 40258810, 2025). "However, most of these studies have focused on the expressions of NDUFS8 rather than the genetic level, which lacks molecular mechanisms of oncogenesis, tumor formation, and progression." (PMID 36557887, 2022). "A combination of lung adenocarcinoma and liver cancer showed that NDUFS8 was overexpressed as well and positively related to long non-coding RNA PPP1R14B-AS1, promoting tumor cell proliferation and migration via the enhancement of mitochondrial respiration." (PMID 36557887, 2022). "In fact, of all protein subunits with significant differences in abundance between tumor and nontumor, only 4 were significantly upregulated in DEN-T: Ndufa13, Ndufs3, Ndufs8, and Ndufv2." (PMID 35756609, 2022).
cancer (6 papers, 2014 to 2025). A tumor composed of atypical neoplastic, often pleomorphic cells that invade other tissues. "When it comes to NDUFS8 and cancer, the techniques above, with a whole landscape of driver mutations, are of great importance to identify whether the NDUFS8 is a structural variant and pathogen of cancer or only the changing levels of NDUFS8 is a symbol of mitochondrial dysfunction." (PMID 36557887, 2022). "Subsequent dot plots and expression density plots demonstrated that NDUFS8 is predominantly expressed in cancer cells and fibroblasts." (PMID 40258810, 2025). "In cancer cells, LonP1 regulates the electron transport chain complex of the oxidative phosphorylation pathway that includes NDUFS8, which modulates the cancer stress phenotype and promotes cancer cell survival." (PMID 36362158, 2022). "On the other hand, the expressions of NDUFS8 vary from cancer to cancer, showing its specific roles in different cancer cells." (PMID 36557887, 2022). "Further investigation into the functional role of NDUFS8 in cancer biology is warranted." (PMID 40258810, 2025). "Despite these findings, studies on NDUFS8 in cancer remain limited." (PMID 40914145, 2025). "Very few studies have explored the expression and potential functions of NDUFS8 in human cancers." (PMID 40258810, 2025). "Additionally, the expression of NDUFS8 in LUAD or LUSC cancer tissues was significantly elevated in comparison to normal lung tissues." (PMID 40258810, 2025). "Furthermore, in LUAD or LUSC cancer tissues, the number of NDUFS8 transcripts was also higher than in their matched surrounding normal tissues." (PMID 40258810, 2025). "Therefore, more extensive studies concerning NDUFS8 in different cancers need to be done with different approaches and aspects." (PMID 36557887, 2022). "Therefore, we summarize the relations between cancer and NDUFS8 of complex I. On the one hand, the level of NDUFS8 shows a prognostic factor for NSCLC and AML in a combination of other subunits in complex I, possibly pointing out a therapeutic target for cancer." (PMID 36557887, 2022). "However, there were still other cancer models not showing the change in NDUFS8 expression, possibly presenting that dysregulation of NDUFS8 may be specific to a few kinds of cancers." (PMID 36557887, 2022). "To assess the potential influence of NDUFS8 on the in vivo growth of NSCLC cells, we conducted a xenograft study employing pNSCLC1 primary cancer cells." (PMID 40258810, 2025). "Within these clusters, NDUFS8 maintained high expression levels, with particularly pronounced expression in the LAMC2 cancer cell group." (PMID 40258810, 2025). "Moreover, its expression increased with cancer progression, suggesting its potential role in tumorigenesis and cancer progression.Within LUAD brain metastases, NDUFS8 expression was significantly elevated in epithelial cells, oligodendrocytes, and fibroblasts." (PMID 40258810, 2025).
infection (4 papers, 2017 to 2025). The state of being infected such as from the introduction of a foreign agent such as serum, vaccine, antigenic substance or organism. "In accordance with the recommendation that at least three reference genes should be used for robust normalization of RT-qPCR data, we propose the use of CYSP, NDUFS8 and YSL8, for future studies involving the effects of GLRaV-3 infection on grapevine gene expression through RT-qPCR." (PMID 34711253, 2021).
degenerative diseases (1 paper, 2025). "In contrast, in PF tissue, genes like ATP5F1A, ATP5PO, SDHB, NDUFS8, SDHA, and COX5A play roles within the neurodegenerative disease pathway, and PF tissue has a positive impact on the process related to degenerative diseases." (PMID 40136641, 2025). "IF regulates lipid metabolism primarily via genes including FABP4, WNT10B, PCK1, PLIN1, LEPR, and ADIPOQ, providing energy for cold adaptation, whereas PF positively influences in vivo degenerative diseases mainly through genes such as ATP5F1A, ATP5PO, SDHB, NDUFS8, SDHA, and COX5A." (PMID 40136641, 2025).
metabolic disorder (1 paper, 2022). "Regardless of the upregulation or downregulation of NDUFS8, the change may contribute to the metabolic disorder of mitochondria, causing related diseases." (PMID 36557887, 2022).
mitochondrial disease (1 paper, 2022). "However, when it comes to mitochondrial diseases, which are some of the most common inherited neurometabolic disorders, the involvement of NDUFS8 should not be overlooked, which might help understand the elucidation of mitochondrial disease mechanisms, gene therapies, and new drugs." (PMID 36557887, 2022).
psychiatric diseases (1 paper, 2022). "Moreover, NDUFS8 can have a relation with neural and psychiatric diseases." (PMID 36557887, 2022).
NDUFS8 also shares sentences with these, for which no sentence is quoted: Neurological Disease (3 papers); encephalomyopathy (2); adrenocortical tumors (1); Alzheimer disease (1); cardiomyopathy (1); Cirrhosis (1); cognitive decline (1); dementia (1); frontotemporal dementia (1); glioblastoma (1); kidney disease (1); liver cancer (1); oral cancer (1); pituitary adenomas (1).